IL18 (interleukin 18)
Diseases named in the same sentence as IL18 in open-access papers (continued):
Sharing a sentence is not in itself a finding about the gene and the disease.
tumor (continued). "In light of this, several groups have developed strategies that set out to restrict IL-18 release or biological activity to the tumor microenvironment." (PMID 41728085, 2026). "NK cells activated with IL-12/IL-15, and IL-12/IL-15/IL-18 co-cultured with MHC- tumor cells, and in each cytokine combination with MHC+ tumor cells caused proliferation inhibition and lysis of tumor cells." (PMID 41840113, 2026). "The localized heat triggers pyroptosis, releasing DAMPs (IL‐18, IL‐1β, and tumor antigens), which enhance tumor immunogenicity." (PMID 41298282, 2026). "The overexpression of IL-18 can suppress the immune system’s attack on tumor cells, thus facilitating tumor immune escape." (PMID 41607541, 2026). "IL-18 exerts tumour-suppressive effects through Th1-type immune response activation and augmentation of cytotoxic T lymphocyte functionality, thereby promoting antitumour immunity." (PMID 40738927, 2025). "STING activation led to IL-18 and IL-1β secretion of macrophages, which enhanced the anti-tumor capability of NK cell by inducing 4-1BBL expression in macrophage and 4-1BB in NK cell, respectively." (PMID 40075527, 2025). "The attenuated hematopoietic cell-derived IL-1β and IL-18 at the tumor site of Nlrp3-knockout (Nlrp3−/−) mice are found to be the key to inflammation and tumorigenesis." (PMID 40141358, 2025). "This activation leads to the release of IL-1β and IL-18, which, in turn, influences the expression of PD-L1 on tumor cells and contributes to the recruitment of immune-suppressive cells within the TME." (PMID 40141358, 2025). "As for IL-18, it primarily exhibits pro-tumor properties across various cancer types, facilitating tumor progression and metastasis through mechanisms such as enhanced angiogenesis, promotion of cell migration, and immune evasion." (PMID 39744568, 2025). "IL‐18, a member of the IL‐1 family, is an important regulator of innate and acquired immune responses and has a crucial role in immune, inflammatory, tumor, and pain processes." (PMID 39957627, 2025). "Conversely, IL18 can also stimulate various tumor cell behaviors, including angiogenesis, proliferation, migration, and immune evasion." (PMID 41257666, 2025). "Concurrently, to determine if 2-DG induces pyroptosis in vivo, expression of caspase-3, GSDME, IL-18, and IL-1β was analysed in tumor tissues." (PMID 41415273, 2025). "We identified IL16 and IRF4 to be broadly downregulated in tumor-infiltrating DCs, CXCR4 to be broadly upregulated, and IL18 and IL22RA2 increases to be associated with cDC2s." (PMID 39932553, 2025). "Emerging evidence, however, reveals the functional dichotomy of IL-18 across heterogeneous cancer types, with its biological outcomes being contingent upon tumour-specific genomic landscapes and microenvironmental cues." (PMID 40738927, 2025). "Integrating IL-18 into CAR-T resulted in increased anti-tumor function, cytokine secretion, survival and T-cell persistence in several studies." (PMID 40722088, 2025). "Consistent with previous reports, IL‐18 was exclusively expressed in the spinal microglia after tumor injection." (PMID 39957627, 2025). "IL-18 deficiency due to NLRP3 loss can impair IFN-γ production as well as STAT1 activation, thereby increasing tumor burdens in CRC." (PMID 41291696, 2025). "Among these, CTSS was uniquely identified as the lysosomal protease capable of cleaving GSDMD, IL‐1β, and IL‐18 independently of caspase‐1, establishing a novel pathway of tumor‐specific pyroptosis induction." (PMID 40539828, 2025). "This approach selectively neutralizes IL-18’s pro-tumor effects within the TME while preserving its systemic immunostimulatory potential, significantly improving survival in murine PC models." (PMID 40948749, 2025). "Currently, strategies are being developed to deliver cytokines such as IL‐12 and IL‐18 to the tumor microenvironment." (PMID 40923840, 2025).
tumor (continued). "Other studies have shown that tumor cells can evade immune recognition and promote tumor cell proliferation and metastasis through IL-18." (PMID 40115022, 2025). "On one hand, IL-18 enhances the activity of cytotoxic T lymphocytes and natural killer (NK) cells, thereby boosting immune responses against tumor cells." (PMID 40656950, 2025). "Anlotinib, a multi-targeted receptor tyrosine kinase inhibitor, promotes M1 macrophage polarization and inhibits M2 polarization by upregulating the secretion of IL-18 from tumor cells." (PMID 41280929, 2025). "IL-18, a critical immunomodulatory cytokine, exhibits pleiotropic and context-dependent functions in tumour immunology." (PMID 40738927, 2025). "These CAR T-cells not only target specific tumor antigens but also secrete cytokines, such as IL-12 or IL-18, to enhance T-cell activation and recruit innate and adaptive immune cells to the tumor site." (PMID 40940995, 2025). "In the early stages of tumorigenesis, TANs are predominantly of the N1 phenotype, exerting anti-tumor functions through the activation of interleukin-18 (IL-18) and the secretion of interferon-beta (IFN-β)." (PMID 41306968, 2025). "Among these, IL-33 and IL-18 play key roles in tumor biology and immunology in different types of cancers, including breast, CRC, and CML." (PMID 40247153, 2025). "Upon activation from tumor ligands, NK cells rapidly produce abundant IFNγ and TNFα in the presence of IL-12/IL-18 derived from activated tumor-resident macrophages and DCs." (PMID 40410571, 2025). "IL-1β, IL-18, and TNF-α are known to be associated with tumour invasion, progression, and metastatic potential." (PMID 40430084, 2025). "To further understand the potential interactions between immune cells, we also performed an analysis of cytokine expression genes in tumours; the most expressed cytokines were TGFβ, IL-18, IL-15, and TNFα." (PMID 41301032, 2025). "AIM2 is essential for producing IL-1β and IL-18 that encourage the accumulation of Treg cells and tumor progression in vivo." (PMID 41291696, 2025). "Unlike traditional apoptosis and necrosis, pyroptosis is more effective in inducing the release of intracellular pro-inflammatory factors, such as IL-1β and IL-18, thereby promoting a robust inflammatory response and reducing tumor resistance." (PMID 40486906, 2025). "IL-18-activated myeloid cells secrete NO, aiding tumor killing but potentially nitrating tumor-specific TCRs, impacting memory differentiation." (PMID 41488627, 2025). "Collectively, these findings suggest that the NFAT1/IL‐18 signaling pathway is involved in tumor‐induced pain hypersensitivity by regulating neuronal activity through modulation of the NMDA receptor." (PMID 39957627, 2025). "A recent study revealed that combining IL-12/IL-18-pretreated NK cells with Sorafenib improved the inhibition of HCC tumor growth." (PMID 41050183, 2025). "The sorafenib- and IL-12/IL-18-pretreated NK cell combination enhanced tumor inhibition by overcoming drug resistance and modulating the immune response." (PMID 40002292, 2025). "To assess the PCa tumour microenvironment for impaired immunity, we also performed a pilot RNA-expression analysis for PCa-associated immunological factors (IL1β, IL10, IL18, TNF-α, TLR4, GATA3, CD68)." (PMID 40430084, 2025). "TMAO can induce gasdermin E (GSDME)-mediated tumor cell pyroptosis by activating the endoplasmic reticulum kinase PERK, leading to release inflammatory factors such as IL-1β and IL-18 into the tumor microenvironment." (PMID 40241220, 2025). "A combination therapy with IL-18 inhibition and anti-PD-1 decreased tumor burden and increased T-cell infiltration." (PMID 40109854, 2025). "First and foremost, the activation of GSDME significantly promotes the infiltration of immune cells into the tumor microenvironment through the release of inflammatory cytokines, such as IL-1β and IL-18." (PMID 40568597, 2025).
tumor (continued). "Repeated intrathecal injections of the IL‐18 inhibitor IL‐18 BP once daily on days 12, 13, and 14 post‐tumor inoculation attenuated tumor‐induced mechanical allodynia, thermal hyperalgesia, and spontaneous pain." (PMID 39957627, 2025). "The authors demonstrated significantly increased expression of IL-18 and its mRNA in tumor tissue compared to physiological tissue, as well as IL-18 expression in papillary ovarian cancer." (PMID 41561739, 2025). "Less restricted targeting and trans activity from potent IL-18 drive myeloid-dependent anti-tumor responses, including M2-to-M1 macrophage repolarization, before T cell memory develops." (PMID 41488627, 2025). "Targeted inhibition of the NF-κB pathway using BAY11–7082 suppresses the promoting effects of IL-18 on tumor proliferation and invasion, enabling IL-18 to act as a co-stimulatory cytokine to facilitate immunotherapy." (PMID 40948749, 2025). "The TTFields and anti-PD-1 treatment group induced more release of IL-1β and IL-18 in tumor than anti-PD-1 treatment alone." (PMID 40098106, 2025). "Induced IL-18 secretion has been demonstrated to improve effecter function and anti-tumor activity of CAR-T against solid cancers." (PMID 40722088, 2025). "Here, we report that IL-18-primed natural killer (NK) cells enhanced the antitumor effects of anti-PD-1 antibodies by mobilizing type 1 conventional dendritic cells (cDC1s) to tumor sites and promoting type 1 immune responses." (PMID 40165899, 2025). "Anlotinib inhibits OC by converting immunosuppressive TAMs to anti-tumor M1 macrophages via the IL-18 axis." (PMID 41280929, 2025). "IL-18 surface display: E. coli displays IL-18 on its surface to stimulate immune cells and target hypoxic tumor microenvironments." (PMID 41522435, 2025). "This process was accompanied by the release of abundant inflammatory factors, such as interleukin-1β (IL-1β) and interleukin-18 (IL-18), which significantly enhanced the recruitment and activation of tumor-infiltrating lymphocytes (TILs) and CD8+ T cells." (PMID 41144097, 2025). "The role of IL-18 in tumourigenesis exhibits dual characteristics, demonstrating both tumour-suppressive and tumour promoting potential." (PMID 40738927, 2025). "Meanwhile, mature IL-18 enhances the activity of NK and T cells, potentially influencing tumor progression." (PMID 40718836, 2025). "In early stage of tumor tissues or normal tissues, where the microenvironment is still subjected to immune surveillance, cytokines secreted by immunocytes, such as IL18 and IL12, can stimulate nuclear translocation of ACAT1 to strengthen antitumor immunity." (PMID 40289129, 2025). "Multiple studies indicate that HIF-1α suppresses NK cell-mediated tumor surveillance by inhibiting the IL-18-dependent NF-κB signaling axis, thereby attenuating anti-tumor responses." (PMID 40791591, 2025). "Upon subsets analysis, we observed that ILC1-like cells’ CD107a expression was significantly lower in the tumor microenvironment compared to the liver when the cells were stimulated with IL-12/IL-18." (PMID 41268557, 2025). "More advanced fourth-generation CARs, known as T cell Redirected for Universal Cytokine Killing, are engineered to secrete immunostimulatory cytokines like IL-12, IL-15, or IL-18, thereby enhancing anti-tumor efficacy and modulating the tumor microenvironment." (PMID 40677703, 2025). "This aligns with evidence on NLRP3 inflammasome activation in tumor progression via IL-1β and IL-18 maturation." (PMID 41373809, 2025). "In an in vivo model of disseminated SCLC, tailored AM dosing and cytokine support through an activation-induced IL-18 armour approach resulted in improved functional persistence and anti-tumour activity of AdCAR-T." (PMID 40722088, 2025). "A large number of inflammatory factors (e.g., IL-1β and IL-18) are released after pore formation, thereby altering the tumor microenvironment, and triggering a strong anti-tumor immune response." (PMID 40011473, 2025).
tumor (continued). "Mechanistic studies indicate that GSDME-mediated pyroptosis can promote tumor antigen presentation and enhance T cell infiltration by releasing inflammatory factors such as IL-1β and IL-18, thereby improving the tumor immune microenvironment." (PMID 40568597, 2025). "In this study, we focused on IL-18-primed NK cells and set out to elucidate how they enhance the anti-tumor effects of ICB therapy." (PMID 40165899, 2025). "Western blot analysis revealed a pronounced increase in IL‐18 expression on day 14 post‐tumor inoculation." (PMID 39957627, 2025). "A more direct approach involves newer generations of CAR T cells designed to release cytokines such as IL-15 or IL-18, which can repolarize myeloid cells at the tumor site, enhancing the anti-tumor efficacy of CAR T cells." (PMID 40050933, 2025). "Innate immune cells, such as mature dendritic cells and M1-tumor-associated macrophages (TAM), produce cytokines (IFN-α, IL-12, IL-18, or TNF-α) and chemokines (CXCL9, CXCL10, or CCL21) that suppress tumor angiogenesis." (PMID 41373757, 2025). "Notably, IL-18 been reported to act synergistically with other pro-inflammatory cytokines to promote antitumor immune responses and potentiate the effects of ICIs, and lower levels of G-CSF are associated with a less immunosuppressive tumor immune microenvironment." (PMID 40258833, 2025). "The results demonstrated that, during the third tumor encounter, IL-18-releasing iTRUCK19.18 cells exhibited a significant enhanced antitumoral activity compared with cells without Dox and standard CAR19 cells." (PMID 39640015, 2024). "Armoring with (m)pro-IL18 marginally improved tumor control compared to m2G-T + nil; however, differences were not significant." (PMID 38745414, 2024). "This strategy is aimed at enhancing relevant cytokines production, e.g., IL-18, and thus enabling the T cells to better infiltrate the solid tumor and to improve their specific function in the impaired immunosuppressive tumor microenvironment." (PMID 39769266, 2024). "Caspase-1, IL-1β, and IL-18 are down-regulated in NSCLC tumor tissues, and simvastatin activates NLRP3-caspase-1-IL-1β and IL-18 pathways to induce pyroptosis and inhibit NSCLC cell migration." (PMID 38654314, 2024). "On the other hand, NLRP3 inflammasome activation can lead to excessive production of inflammatory cytokines such as IL-1β and IL-18, significantly affecting the tumor microenvironment and potentially promoting HCC growth." (PMID 39544286, 2024). "The rationale behind it is that in a certain cancer microenvironment, IL-18 activates anti-tumor effector cells, such as T and NK cells, but the tumor uses IL-18’s natural antagonist, IL-18BP, to block this activity and thus evades the host’s immune system." (PMID 39769266, 2024). "It has also been suggested that the NLRP3 inflammasome can activate the tumor suppressor STAT1 in the colon through IL-18-mediated interferon gamma (IFN-ɣ) production." (PMID 38182564, 2024). "Based on the role of IL-18 signaling in tumor immunotherapy, additional innovation combines cancer checkpoint therapy with IL-18 signaling." (PMID 39769266, 2024). "IL-18, a pro-inflammatory cytokine, plays a significant role in anti-tumor immunity through several mechanisms." (PMID 38957317, 2024). "In the PDA7940b tumor model, significantly more IL-18, IFNγ, and IL-2 was detected in mouse serum from the combination treatment group comparted to CART alone." (PMID 38730243, 2024). "Specifically, BHLHE40 was expressed in 73% of tumour tissues, while IL18 was universally present in 100% of tumours." (PMID 38254861, 2024). "Instead, we demonstrate the therapeutic potential of a transient deconstruction of inflammasomes in tumor cells with either IL-1β or IL-18 in combination with pyroptosis." (PMID 39737979, 2024).
tumor (continued). "In this study, stimulation of NK cells with PM21-particles derived from K562-41BBL-mbIL21 cells was combined with memory-like induction using cytokines IL-12, IL-15, and IL-18 to produce NK cells with enhanced anti-tumor function." (PMID 38711506, 2024). "Specifically, after pyroptosis, the cells promote the release of cytokines such as IL‐1β and IL‐18, which can have an effect on tumour development and metastasis." (PMID 38652105, 2024). "No IL18 biological activity was detected when trunc.pCAR-H/T + GzB-IL18 T cells were co-cultured with MDA-MB-468 tumor cells." (PMID 38745414, 2024). "Therapeutic T cell armoring with IL18 promotes autocrine stimulation and positive modulation of the tumor microenvironment (TME)." (PMID 38745414, 2024). "NLRP3 inflammasome activation, such as IL-1β and IL-18 production, promotes immune cell infiltration in the tumor microenvironment and enhances chemotherapy-induced anti-tumor immunity." (PMID 38575922, 2024). "High levels of IL-18 exert pro-tumorigenic effects by participating in angiogenesis, tumor cell invasion, and metastasis." (PMID 38553639, 2024). "The proinflammatory cytokines IL-15, IL-18, and IL-1β profiles reveal a significant host serum increase after day 35 when the tumor began to progress in growth." (PMID 39451257, 2024). "The invention of IL-18 with “decoy resistance” (DR-18) overcome this restriction and demonstrated powerful anti-tumor activity." (PMID 38727246, 2024). "Here the authors report a toolbox of gasdermin D variants for induction of pyroptosis, showing that, when combined with intratumoral expression of cytokines (IL-1β, IL-12, or IL-18), anti-tumor immune responses in preclinical models are enhanced." (PMID 39737979, 2024). "IL-13 and IL-18 play complex and diverse roles in the development of cancer, involving not only tumor growth, dissemination, and immune evasion mechanisms but also providing new targets for cancer prognostic biomarkers and therapeutic interventions." (PMID 39267832, 2024). "IL-18 signaling promotes the activation and expansion of NK cells and improves their cytotoxicity and tumor activity, as well as the CD80, CD86, and HLA-DR expression in APCs." (PMID 39599846, 2024). "Firstly, IL-18 activates natural killer (NK) cells and certain subsets of T cells, enhancing their cytotoxic activity against tumor cells by upregulating cytotoxic molecules such as perforin and granzymes, which are crucial for direct tumor cell killing." (PMID 38957317, 2024). "Taken together, cultivation based on IL-15 or IL-18 stimulation should be considered when appropriate persistency and anti-tumor functions of Vγ9Vδ2 T cells are required." (PMID 38221530, 2024). "In the control-treated tumor, IL-1 signaling, including IL-1A, IL-1β, and IL-18, appeared to be the dominant cytokine-type ligand-receptor interaction between macrophages/granulocytes and CAFs." (PMID 39298276, 2024). "Future studies are needed to elucidate the precise role of IL-18 in tumor initiation, progression, and antitumor defense." (PMID 38391959, 2024). "IL-18, a pro-inflammatory cytokine, exhibits a dual role in cancer by enhancing anti-tumor immunity while promoting tumor growth and metastasis through a pro-inflammatory microenvironment, correlating with poor prognosis when elevated." (PMID 39064604, 2024). "IL18 also enhances the expansion and intrinsic anti-tumor activity of NK9 and γδ T cells, innate cell types with attractive properties for allogeneic CAR-based immunotherapy." (PMID 38745414, 2024). "Preclinical delivery of anti-IL-18 therapy, alongside anti-PD-1, decreased MDSCs, increased T lymphocyte infiltration, and reduced overall tumor burden." (PMID 39333065, 2024). "The protein expression level of NLRP3, caspase 1, GSDMD, IL-1β and IL-18 in XRZYBXD high dose group were also significantly higher than those in the tumor model group by WB." (PMID 40046008, 2024).